FZD6 (frizzled class receptor 6)
Diseases named in the same sentence as FZD6 in open-access papers (continued):
Sharing a sentence is not in itself a finding about the gene and the disease.
esophageal cancer (2 papers, 2020 to 2025). A primary or metastatic malignant neoplasm involving the esophagus. "Esophageal cancer specimens exhibit co-overexpression of Wnt2 and Wnt5A, as well as receptors such as FZD2 and FZD6, which are linked to worse prognosis and reduced survival." (PMID 40943055, 2025). "In agreement with this, increased expression of FZD6 has been reported in many cancer types, and correlates with poor prognosis in patients with breast, brain and esophageal cancer." (PMID 32245826, 2020).
liver cancer (2 papers, 2018 to 2020). An epithelial or non-epithelial malignant neoplasm that arises from the liver. "Divergent lncRNA of FZD6 (lncFZD6) recruits the BRG1 (Brahma-related gene 1; SMARCA4)-embedded SWI/SNF complex to the FZD6 promoter, driving the FZD6 transcription in liver cancer." (PMID 32429086, 2020). "To further examine the expression pattern of FZD6, we collected liver cancer samples, examined the expression levels of FZD6 with real-time PCR and western blot, and confirmed the increased FZD6 expression both at mRNA levels and protein levels." (PMID 29535420, 2018). "What’s more, a divergent lncRNA of FZD6, termed lncFZD6, is also highly expressed in liver cancer and liver TICs." (PMID 29535420, 2018). "Here, we investigated the expression profile of Wnt receptors in tumorigenesis and liver TICs, and found FZD6 is highly expressed in liver cancer and liver TICs." (PMID 29535420, 2018). "Here we found FZD6 is highly expressed in liver cancer and liver TICs." (PMID 29535420, 2018). "Here, we found lncFZD6 and FZD6 are highly expressed in liver cancer cells and liver TICs." (PMID 29535420, 2018). "Altogether, FZD6 is highly expressed in liver cancer and liver TICs." (PMID 29535420, 2018).
Nail dystrophy (2 papers, 2014 to 2016). Onychodystrophy (nail dystrophy) refers to nail changes apart from changes of the color (nail dyschromia) and involves partial or complete disruption of the various keratinous layers of the nail plate. "FZD6 screening should be considered for any spontaneous cases or known recessive cases with isolated nail dystrophy." (PMID 24611874, 2014).
oral squamous cell carcinoma (2 papers, 2022). "Among these, as an example, is mir-302b, a microRNA we have identified in our IPA analysis, which was shown to target FZD6 in oral squamous cell carcinoma to promote cell invasion and migration." (PMID 35237656, 2022).
pancreatic cancer (2 papers, 2014 to 2024). "Collectively, these data indicate that WNT7A/7B ligands and WNT receptors FZD1 and FZD6 mediate the paracrine signalling between pancreatic cancer cells and stellate cells in the tumour." (PMID 38678032, 2024).
thymic carcinoma (2 papers, 2022 to 2025). Thymic carcinoma (TC) is a type of thymic epithelial neoplasm characterized by a high malignant potential. "Resent research investigates the role of WNT4 signaling in TETs, finding that WNT4 and its receptor FZD6 are overexpressed in aggressive B3 thymoma and thymic carcinoma, unlike their age-related decline in normal thymus." (PMID 40805209, 2025). "Expression and function of WNT4 and FZD6 were analyzed using qRT–PCR, Western blot, ELISA, in biopsies of non-neoplastic thymi (NT), thymoma and thymic carcinomas." (PMID 35965500, 2022).
thymoma (2 papers, 2022 to 2025). A neoplasm arising from the epithelial cells of the thymus. "High levels of FZD6 mRNA were a recurrent finding in all aggressive TETs (B2, B3 thymomas, and TCs)." (PMID 35965500, 2022). "This is a key new finding that WNT4/FZD6 appears to be particularly relevant for developing the most aggressive TETs (B3 thymomas and TCs) since they showed the most abnormally increased mRNA levels of WNT4/FZD6." (PMID 35965500, 2022). "Considering that the most aggressive TETs, B3 thymomas, and TCs showed combined increased expression of WNT4, its non-canonical frizzled receptor 6 (FZD6), and downstream non-canonical WNT/JNK activity, TETs appear as promising candidates for trials testing novel inhibitors of WNT and JNK." (PMID 35965500, 2022).
adenoma (1 paper, 2008). A neoplasm arising from the epithelium. "Frizzleds 4, 6 and 10 showed less obvious changes, with a tendency to become expressed in the adenomas, the increased incidence of FZD6 just reaching significance (P<0.04)." (PMID 18414471, 2008). "While some Frizzleds (FZDs) were downregulated in adenomas, the Wnt/Ca2+ receptors FZD3 and FZD6 were induced by a median factor of 6.5 and 4.6, respectively." (PMID 18414471, 2008).
Alzheimer disease (1 paper, 2023). A progressive, neurodegenerative disease characterized by loss of function and death of nerve cells in several areas of the brain leading to loss of cognitive function such as memory and language. "Using bioinformatics analysis, we found that the mRNA expression levels of frizzled class receptor 6 (FZD6) and proteasomal subunit α4s (PSMA8), which associated with the Wnt signaling pathway and Alzheimer disease, were downregulated in the vitreous of patients with PDR." (PMID 36899334, 2023).
and acute leukemia (1 paper, 2013). "Among these overlapped regions, several functional genes were found, including LIM and senescent cell antigen-like domains 1 (LIMS1), myosin light chain kinase family, member 4 (MYLK4), frizzled family receptor 6 (FZD6), and brain and acute leukemia, cytoplasmic (BAALC)." (PMID 23390598, 2013).
basal cell carcinoma (1 paper, 2022). A carcinoma involving the basal cells. "Our analysis showed that FZD6 is implicated in several signalling pathways including BC, Wnt, cancer-related (such as the epithelial-mesenchymal transition (EMT)), and basal cell carcinoma signalling pathways." (PMID 35237656, 2022).
bladder cancer (1 paper, 2020). "Mechanistically, we found that CASC9 functions as a miRNA sponge to positively regulate FZD6 expression and subsequently activates Wnt/β-catenin signaling pathway, thus playing an oncogenic role in bladder cancer pathogenesis." (PMID 32677984, 2020). "The CASC9/miR-497-5p/ FZD6 axis provides insights for regulatory mechanism of bladder cancer, and new strategies for clinical practice." (PMID 32677984, 2020). "Moreover, CASC9 and FZD6 were co-expressed in bladder cancer cells." (PMID 32677984, 2020). "Meanwhile, we found knockdown of CASC9 decreased FZD6 and inhibited EMT of bladder cancer cells in vivo." (PMID 32677984, 2020).
brain tumour (1 paper, 2016). "Re-expression of shRNA-resistant FZD6 in MES spheres rescued their ability for cell growth and sphere formation in vitro, and restored brain tumour xenograft growth that was reduced by FZD6 knockdown." (PMID 27698350, 2016).
breast adenocarcinoma (1 paper, 2022). "IPA analysis results showed that FZD6 is implicated in BC, breast adenocarcinoma, and ductal breast carcinoma molecular signalling." (PMID 35237656, 2022). "The IPA analysis also showed that FZD6 is implicated in breast adenocarcinoma, and ductal breast carcinoma." (PMID 35237656, 2022).
Caudal Regression syndrome (1 paper, 2012). "The FZD6 p.Arg511His (c.1532G>A) was found in an Italian patient with Caudal Regression syndrome, including vertebral and costal anomalies, meningocele, hydromyelia, tethered cord, left kidney agenesis; it is predicted to localize to the cytoplasmatic terminal domain of the protein." (PMID 22045688, 2012).
colorectal adenoma (1 paper, 2008). An adenoma that arises from the colon or rectum. "Since the qualitative review of expression indicated induction of NKD1, FZD3 and FZD6 in colorectal adenomas, we developed quantitative real-time RT–PCR assays for each of these to determine the extent of the induction." (PMID 18414471, 2008). "In this paper, we show that NKD1, FZD3 and FZD6 transcripts are all induced significantly in colorectal adenomas compared to matched normal tissue, indicating that both the Wnt/PCP and the Wnt/Ca2+-response pathways are expressed at an early stage in tumour formation." (PMID 18414471, 2008).
Crohn disease (1 paper, 2017). A gastrointestinal disorder characterized by chronic inflammation involving all layers of the intestinal wall, noncaseating granulomas affecting the intestinal wall and regional lymph nodes, and transmural fibrosis. "In addition, FZD6 was highly expressed in intestine mucosal layer of adult human patients with ulcerative colitis (UC) and Crohn's disease, however, the precise function of FZD6 in the small intestine is not clear." (PMID 28614361, 2017).
cutaneous squamous cell carcinoma (1 paper, 2025). "Alterations in Wnt signaling have also been observed in cutaneous squamous cell carcinoma with which PeSCC is most analogous; these include upregulation of WNT5A and FZD6 and raised levels of β-catenin." (PMID 40486660, 2025).
endometriosis (1 paper, 2025). The growth of functional endometrial tissue in anatomic sites outside the uterine body. "Wnt protein binding (GOMF) was a significant pathway in our gene set analyses, with five genes overlapping with our biologically-implicated endometriosis gene set: CTHRC1 (mSMR), FZD6 (fibroblast-eSMR), PTPRO (fibroblast-, ovary-, and whole blood-TWAS), RECK (fibroblast-sSMR), and TRABD2A (mSMR)." (PMID 41377979, 2025).
hydromyelia (1 paper, 2012). "Genotype–phenotype correlation shows that this de novo and severe FZD6 mutation is associated with a complex dysraphic state in a patient presenting with thoracic meningocele, spondylo-costal malformations, hydromyelia, and lipoma." (PMID 22045688, 2012).
invasive breast carcinoma (1 paper, 2020). A carcinoma that infiltrates the breast parenchyma. "Negative regulator of Wnt oncogenic signaling, Frizzled receptor 6 (FZD6) is also hypermethylated in invasive breast cancer." (PMID 32051475, 2020).
leiomyoma (1 paper, 2022). A well-circumscribed benign smooth muscle neoplasm characterized by the presence of spindle cells with cigar-shaped nuclei, interlacing fascicles, and a whorled pattern. "Earlier reports showed Wnt4 was primarily expressed in leiomyoma intermediate and differentiated cells, while FZD6 was predominantly expressed in stem cells." (PMID 35118811, 2022).
lung carcinoma (1 paper, 2011). "Next, we performed quantitative PCR on three Wnt pathway genes (FZD6, DVL3, WNT5A) in a commercial panel of 40 lung cancer samples (Origene; Rockville, MD)." (PMID 22016777, 2011).
myelomeningocele (1 paper, 2012). Myelomeningocele is the most severe form of spina bifida. "Our present data of a novel predicted altered miRNA binding site of FZD6 gene in a patient with myelomeningocele adds to the already complex picture of NTDs pathogenesis." (PMID 22045688, 2012). "The FZD6 p.Arg511Cys (c.1531C>T) was identified in an Italian patient with myelomeningocele (MMC)." (PMID 22045688, 2012).
myocardial infarction (1 paper, 2023). Gross necrosis of the myocardium, as a result of interruption of the blood supply to the area, as in coronary thrombosis. "Among them, FZD6 is regarded as the receptor of WNT signaling pathway, which has been reported to be involved in the development of myocardial infarction 45-53." (PMID 36923925, 2023).
nasal polyps (1 paper, 2023). "The expression levels of DVL1, DVL3 and FZD3 mRNAs were significantly lower in the nasal polyps than in the turbinates, while those of FZD6, PRICKLE1, PRICKLE2, VANGL1 and VANGL2 mRNAs were not statistically different between the two tissues." (PMID 38232516, 2023).
osteoarthritis (1 paper, 2024). A noninflammatory degenerative joint disease occurring chiefly in older persons, characterized by degeneration of the articular cartilage, hypertrophy of bone at the margins and changes in the synovial membrane. "In conclusion, we found that miR-199b-5p is elevated in osteoarthritis and may affect cell viability and related cytokines by potentially targeting Gcnt2 and Fzd6." (PMID 38770735, 2024).
psoriasis (1 paper, 2009). An autoimmune condition characterized by red, well-delineated plaques with silvery scales that are usually on the extensor surfaces and scalp. "We included Fzd3 and Fzd5 in this analysis, since these have been reported to bind Wnt5a, as well as Fzd6, as it was found upregulated in psoriasis and squamous cell carcinoma." (PMID 19399181, 2009). "We next characterized the expression of Wnt5a, Fzd3, Fzd5, Fzd6 in psoriasis lesions which are characterized by hyperproliferation and dysregulated differentiation." (PMID 19399181, 2009). "Taken together, Wnt5a, Fzd5, and Fzd6 are strongly upregulated in psoriasis." (PMID 19399181, 2009).
skin aging (1 paper, 2025). The gradual irreversible changes in structure of skin that occur as a result of the passage of time.. "In this study, we explored the protective function of HOXC10 against skin aging and demonstrated that HOXC10 activates the canonical Wnt/β-catenin signaling pathway by suppressing frizzled 6 (FZD6) transcription, thereby delaying the cell senescence and skin aging processes." (PMID 41268215, 2025).
T-cell acute lymphoblastic leukemia (1 paper, 2023). Acute lymphoblastic leukemia of T-cell origin. "WNT10B also interacted with FZD6 in a T-cell acute lymphoblastic leukemia cell line and HEK293T cells, as demonstrated by immunoprecipitation and PLA." (PMID 36814601, 2023).
urothelial carcinoma (1 paper, 2020). A malignant neoplasm derived from the transitional epithelium of the urinary tract (urinary bladder, ureter, urethra, or renal pelvis). "Interestingly, some of these genes, such as ETV4, PTGES, CTBP2, FZD6, EAF2, and IKZF6, have not been implicated in urothelial carcinoma; thus, these genes are potential candidates for diagnostic, prognostic, and therapeutic biomarkers of urothelial carcinoma." (PMID 32391279, 2020).
tumor (48 papers, 2008 to 2025). "In liver tumourigenesis, FZD6 was the only frizzled gene found to be associated with tumour recurrence and metastasis." (PMID 35237656, 2022). "Expression pattern analysis of FZD6 in a Saudi BC cohort showed that its elevated expression is associated with tumour invasion, metastasis, and worse survival outcomes mainly in younger patients." (PMID 35237656, 2022). "In the current study, we showed that elevated FZD6 expression is strongly associated with the early onset of female Saudi BC patients, tumour invasion, and poor survival outcomes." (PMID 35237656, 2022). "In COSCC, we noticed an association among the tumor differentiation of cell keratinization and FZD6 expression." (PMID 34072517, 2021). "The invasive front with areas of tumor budding exhibited high FZD6 expression with a loss of cytokeratin expression." (PMID 34072517, 2021). "Areas of tumor budding in the invasive front displayed high FZD6 expression with a loss of cytokeratin expression." (PMID 34072517, 2021). "Consistently, inhibition of FZD6 also markedly reduced MES-associated CD44 expression in MES brain xenograft tumours." (PMID 27698350, 2016). "It includes receptors that have been mechanistically linked to cancer progression such as the G protein coupled receptors CXCR3 and FZD6, linked to tumor cell growth, invasion and migration, and PTPN22, a protein tyrosine phosphatase associated with inhibition of antioncogenic immune response." (PMID 35875157, 2022). "Immunostaining of BrdU shows that the proliferation indices of tumor cells decreased in both models by 54% upon FZD6 knockdown." (PMID 41286306, 2025). "Consistent with the tumor inhibitory effect of FZD6 knockdown, the activities of proteins that promote tumor growth including SRC, AKT1, and STAT3 were decreased." (PMID 41286306, 2025). "Combinatorial treatment with FZD6 knockdown and cisplatin further reduced the average tumor volume to 301.6 mm3 and significantly increased survival of the experimental mice." (PMID 41286306, 2025). "Meanwhile, LINC00659 promotes tumor cell growth by regulating the stability of frizzled class receptor 6 (FZD6) mRNA in digestive tract tumors in an IGF2BP1-dependent manner." (PMID 40584294, 2025). "It was discovered that expressions of FZD2 and FZD6 (especially FZD2) were strongly and positively correlated with M2-type markers of tumor-associated macrophages (TAMs)." (PMID 36699699, 2022). "At 5 years follow up time, about 67% of BC patients who had tumours with high FZD6 expression died compared to only 27% death rate for those with a low FZD6 expression pattern (p < 0.02, log-rank)." (PMID 35237656, 2022). "This was mainly due to the overall patients’ cohort where tumours with FZD6 elevated expression showed higher recurrence rates (DFS, p < 0.0001, log-rank) and shorter survival times (DSS, p < 0.02, log-rank)." (PMID 35237656, 2022). "In fact, tumours with high grade (poorly differentiated cells character) showed higher FZD6 expression pattern as compared to well and moderately differentiated tumour cells (p = 0.04)." (PMID 35237656, 2022). "FZD6 expression analysis showed a significant correlation with tumour invasion (p < 0.05), and borderline significance with tumour grade (p = 0.07)." (PMID 35237656, 2022). "BC tissues with high invasiveness character expressed more FZD6 protein than less invasive tumours (p < 0.003)." (PMID 35237656, 2022). "MicroRNAs targeting Fzd6 have mostly been described as tumor-suppressive; however, Fzd6 has been shown to be both upregulated and downregulated in various cancers." (PMID 34671643, 2021). "Both DLX6-AS1 and CASC9 sponge miRNA miR-497-5p, which increases Fzd6 expression, along with tumor growth and metastasis in pancreatic cancer and bladder cancer, respectively." (PMID 34671643, 2021). "In the oncogenic subnetwork, the overexpression of FZD6 targeted by miR-140-5p, miR-92a-3p, and miR-199a-5p as the known tumor suppressors were observed in ATLL." (PMID 33630973, 2021).